FOXR2 (forkhead box R2)
Diseases named in the same sentence as FOXR2 in open-access papers (continued):
Sharing a sentence is not in itself a finding about the gene and the disease.
brain tumors (9 papers, 2020 to 2025). "Beyond CNS NB-FOXR2, this model can be readily expanded to explore other brain tumor subtypes associated with FOXR2 alternations." (PMID 39220247, 2024). "Profiling the developing brain enabled rationally guided modeling of FOXR2-activated CNS neuroblastoma, providing a strategy to overcome the heterogeneous origins of pediatric brain tumors that hamper tumor modeling and therapy development." (PMID 39495206, 2025). "Identifying these factors in the FOXR2 network offers potential avenues for more precise targeted therapies, enhancing outcomes in pediatric brain tumors." (PMID 39220247, 2024). "CNS NB-FOXR2 consists of less than 3% of all high-grade pediatric brain tumors, and alterations at the FOXR2 locus are rarely examined for diagnosis." (PMID 39220247, 2024). "CNS neuroblastoma with forkhead box R2 (FOXR2) activation (CNS_NBL) emerged as a distinct pediatric brain tumor entity from a pool previously diagnosed as primitive neuroectodermal tumors of the central nervous system (CNS-PNETs)." (PMID 33536079, 2021). "This activation was due to the gain of the oncogenic FOXR2 promoter in a pediatric brain tumor." (PMID 39866234, 2025). "It was also reported that abnormal FOXR2 activation could lead to the methylome profile and cancer in pediatric brain tumors." (PMID 39866234, 2025). "Future work will involve modeling these and other drivers of brainstem and forebrain pediatric brain tumors, such as alterations in EZHIP and FOXR2, which have been associated with hindbrain ependymomas and forebrain gliomas arising from similar progenitor niches as those targeted in this study." (PMID 37011011, 2023). "We then compared the transcriptome profiles of DMGs with FOXR2 overexpression (n = 10) with non-FOXR2-activated DMGs (n = 29), as well as the profiles of all tumors with FOXR2 overexpression (n = 32) with brain tumors lacking FOXR2 activation (n = 303)." (PMID 40237561, 2025).
embryonal tumors (9 papers, 2022 to 2025). "CNS embryonal tumors other than medulloblastoma include atypical teratoid/rhabdoid tumor (ATRT), embryonal tumor with multilayer rosettes (ETMR), and CNS neuroblastoma with FOXR2 activation." (PMID 40864821, 2025). "This category includes specific subtypes, such as embryonal tumor with multilayered rosettes (ETMR); CNS neuroblastoma, FOXR2-activated; and atypical teratoid/rhabdoid tumor (AT/RT), in addition to a broader designation of CNS embryonal tumor (not otherwise specified; NOS)." (PMID 35454009, 2022).
neuroepithelial tumor (8 papers, 2017 to 2023). "CNS Neuroblastoma with FOXR2 activation (CNS NB-FOXR2), CNS Ewing Sarcoma Family Tumor with CIC alteration (CNS EFT-CIC), CNS high-grade neuroepithelial tumor with MN1 alteration (CNS HGNET-MN1), and CNS high-grade neuroepithelial tumor with BCOR alteration (CNS HGNET-BCOR)." (PMID 32650833, 2020).
ovarian carcinoma (6 papers, 2021 to 2025). A malignant neoplasm originating from the surface ovarian epithelium. "Overexpression of FOXR2 is linked to metastasis and tumor progression, particularly in ovarian cancer, where it correlates with worse histologic grade and poor survival." (PMID 39866234, 2025). "High FOXR2 levels are associated with larger tumors, metastases, and drug resistance, particularly in breast and ovarian cancers, highlighting its potential for more precise diagnosis and treatment strategies." (PMID 39866234, 2025). "The high expression of FOXR2 is also related to the paclitaxel (PTX)-resistance of ovarian cancer cell lines." (PMID 39866234, 2025). "FOXR2 overexpression in ovarian cancer enhances angiogenesis and triggers the hedgehog signaling pathway, which partly explains the aggressiveness of cancer cells." (PMID 39866234, 2025). "Real-time PCR studies showed that PTX-resistant ovarian cancer tissues had more FOXR2 than PTX-sensitive ones." (PMID 39866234, 2025). "They found that circCELSR1, a circular RNA, increased FOXR2 expression by sequestering miR-1252 in Paclitaxel-resistant ovarian cancer cells." (PMID 39866234, 2025). "CircCELSR1 shared the same response element with miR-1252 and bound competitively with miR-1252 to regulate FOXR2 expression, which in turn reduced the sensitivity of ovarian cancer cells to Tax." (PMID 36760722, 2023). "Mechanistically, circCELSR1 was revealed to sponge miR-1252 and subsequently inhibit the expression of FOXR2 in ovarian cancer cells." (PMID 38152652, 2023). "CircCELSR1 regulates the miR-1252/forkhead box R2 (FOXR2) axis to facilitate paclitaxel resistance in ovarian cancer." (PMID 34660304, 2021). "Inhibition of circCELSR1 could enhance sensitivity to paclitaxel in ovarian cancer cells vis FOXR2 /miR-1252 axis." (PMID 37608665, 2024). "FOXR2 may affect the outcome of patients with PTX-resistant ovarian cancer." (PMID 39866234, 2025). "Hence, circCELSR1 promoted PTX resistance via targeting miR-1252/FOXR2 axis in ovarian cancer." (PMID 38152652, 2023). "The research findings reveal a complex interplay where FOXR2 not only governs the carcinogenic traits and epithelial-mesenchymal transition (EMT) in ovarian cancer (OC) cells but also enhances the Hedgehog signaling pathway." (PMID 39866234, 2025). "Additionally, circANKRD17 (also known as circ 0007883), another circular RNA, confers paclitaxel resistance in ovarian cancer by binding to FUS, an RNA-binding protein, and stabilizing FOXR2." (PMID 39866234, 2025). "Therefore, circANKRD17 facilitated PTX resistance in ovarian cancer cells via interaction with FUS and maintenance of FOXR2 stability." (PMID 38152652, 2023).
breast carcinoma (5 papers, 2017 to 2025). "High FOXR2 levels are linked to larger tumors and lymph node metastases in breast cancer patients." (PMID 39866234, 2025). "FoxR2 is overexpressed in breast cancer cells and associated with poor prognosis." (PMID 28915588, 2017). "They found that both FOXR2 protein and mRNA levels were higher in breast cancer samples than in normal breast tissues." (PMID 39866234, 2025). "Furthermore, statistical analysis confirmed FOXR2 as a standalone prognostic indicator for breast cancer." (PMID 39866234, 2025). "Breast cancer cell lines and primary breast tumors were both shown to overexpress FOXR2." (PMID 39866234, 2025). "FOXR2 may also possibly be a significant molecular marker in the diagnosis and prognosis of breast cancer." (PMID 39866234, 2025).
central nervous system neuroblastoma (5 papers, 2020 to 2026). "Central nervous system neuroblastoma with forkhead box R2 (FOXR2) activation (NB-FOXR2) is a high-grade tumor of the brain hemispheres and a newly identified molecular entity." (PMID 39495206, 2025). "One recently identified subtype, FOXR2-activated central nervous system neuroblastoma (CNS NB-FOXR2), is characterized by genomic rearrangements at the Forkhead box gene R2 (FOXR2) locus." (PMID 39220247, 2024).
lung cancer (4 papers, 2021 to 2025). A malignant neoplasm involving the lung. "PJA1 has been linked to the regulation of apoptosis by promoting forkhead box R2 (FOXR2) degradation in lung cancer cells, highlighting its multifaceted role in cell death through the ubiquitination and degradation of key proteins." (PMID 40908564, 2025). "It has been found that circ-ABCB10 can sponge miR-1252 and miR-584-5p in non–small cell lung cancer cells and accordingly stimulate the expression of the downstream targeted genes FOXR2 and E2F5." (PMID 35646916, 2022). "The authors of the study hypothesized that the biomarker FOXR2 may be used to diagnose and predict lung cancer and serve as a possible treatment target, which is an exciting field to explore." (PMID 39866234, 2025). "In addition, circ-ABCB10 was reported to sponge miR-145-5p, affecting the miR-620/FABP5 axis, miR-1252 FOXR2, and miR-670-3p in oral squamous cell carcinoma, glioma, non–small cell lung cancer, and esophageal squamous cell carcinoma, respectively." (PMID 35646916, 2022). "Besides, circABCB10 enhances migration and proliferation of lung cancer by miR-1252/FOXR2 signaling." (PMID 34015764, 2021).
prostate carcinoma (4 papers, 2017 to 2025). A carcinoma that arises from epithelial cells of the prostate gland. "Specifically, in prostate cancer, FOXR2 is vital for cell growth and spread, functioning through the suppression of the Wnt/β-catenin signaling pathway, which is instrumental in the disease’s advancemen." (PMID 39866234, 2025). "As examples, the regulatory mechanism of HOTAIR in prostate cancer was to sponge miR-152 to increase the expression of FOXR2, modulating proliferation and apoptosis of prostate cancer cells." (PMID 31889897, 2019). "In prostate cancer, FOXR2 was overexpressed in prostate cancer cell lines and the knockdown of FOXR2 significantly repressed the proliferation, migration, and invasiveness of prostate cancer cells." (PMID 28827892, 2017). "The TF FOXR2 promotes prostate cancer cell migration, proliferation, and invasion by increasing MMP-2 expression and activity, decreasing p27 expression and nuclear localization, and activating the β-catenin/cyclinD1/c-Myc pathway, as shown by FOXR2 knockdown experiments." (PMID 39866234, 2025). "However, more research is needed to elucidate the role and exact mechanism of FOXR2 in prostate cancer." (PMID 39866234, 2025). "Additionally, lncRNA HOTAIR was observed to interact with miR-152, resulting in upregulation of FOXR2 and further promoting prostate cancer progression." (PMID 39606232, 2024). "Therefore, the therapeutic target FOXR2 may have promise for the treatment of prostate cancer." (PMID 39866234, 2025). "Therefore, FOXR2 could be a potential therapeutic target for treating prostate cancer." (PMID 39866234, 2025).
diffuse midline glioma (3 papers, 2021 to 2025). A diffuse glioma that arises from the midline structures of the central nervous system. "Numerous cancers, including pediatric high-grade gliomas and diffuse midline gliomas, thyroid cancer, Hodgkin lymphoma, and osteosarcoma, were found to have FOXR2 upregulated." (PMID 39866234, 2025).
hepatocellular carcinoma (2 papers, 2017 to 2019). A malignant tumor that arises from hepatocytes. "FoxR2 is also high expressed in human hepatocellular carcinoma and promotes proliferation of tumor cells." (PMID 28915588, 2017). "FOXN6 (FOXR2) regulates the proliferation of the hepatocellular carcinoma cells, and dysregulation promotes tumor formation in chronic hepatocellular carcinoma (HCC)." (PMID 31214487, 2019).
osteosarcoma (2 papers, 2020 to 2025). A usually aggressive malignant bone-forming mesenchymal neoplasm, predominantly affecting adolescents and young adults. "Dysregulation of FOXR2 has been linked to numerous malignant tumors, spanning the brain, nervous system, thyroid, osteosarcoma, Hodgkin lymphoma, colorectal, liver, pancreatic, lung, breast, ovarian, prostate, female genital tract, endometrial, and uterine cancers." (PMID 39866234, 2025). "Further research could lead to the development of targeted therapies aimed at inhibiting FOXR2 to treat osteosarcoma effectively." (PMID 39866234, 2025). "FOXR2 plays a significant oncogenic role in osteosarcoma by promoting cell proliferation." (PMID 39866234, 2025). "Osteosarcoma tissues and cell lines express high levels of FOXR2." (PMID 39866234, 2025). "In osteosarcoma, miR-202 acts as a tumor suppressor by targeting FOXR2." (PMID 39866234, 2025).
cerebral tumors (1 paper, 2025). "Structural rearrangement is the preferred mechanism of FOXR2 activation in cerebral tumors, including non-DMG HGGs and CNS NB." (PMID 40237561, 2025).
Hodgkins lymphoma (1 paper, 2025). A heterogeneous group of malignant lymphoid neoplasms of B-cell origin characterized histologically by the presence of Hodgkin and Reed-Sternberg (HRS) cells in the vast majority of cases. "However, the FOX family of genes, to which FOXR2 belongs, has been implicated in the pathology of Hodgkin lymphoma." (PMID 39866234, 2025).
liver cancer (1 paper, 2025). An epithelial or non-epithelial malignant neoplasm that arises from the liver. "Many breast, lung, and liver cancer cell lines and tumor samples express high levels of FOXR2, and lowering FOXR2 expression in a xenograft model slows down tumor growth." (PMID 39866234, 2025). "Further in vitro and preclinical studies are needed to elucidate the function and mechanism of FOXR2 in liver cancer." (PMID 39866234, 2025).
metastatic disease (1 paper, 2025). "Patients with DMG with FOXR2 overexpression were younger at diagnosis (6.0 vs 9.1 years, P = 0.007), but rates of metastatic disease at diagnosis, gender, and extent of resection were similar." (PMID 40237561, 2025).
non-small cell lung carcinoma (1 paper, 2025). A group of at least three distinct histological types of lung cancer, including non-small cell squamous cell carcinoma, adenocarcinoma, and large cell carcinoma. "FOXR2 downregulation suppresses non-small cell lung cancer cell growth and invasion through the Wnt/β-catenin signaling pathway." (PMID 39866234, 2025).
thyroid cancer (1 paper, 2025). "Furthermore, FOXR2 overexpression is associated with tumor aggressiveness and poorer patient outcomes in thyroid cancer." (PMID 39866234, 2025). "Moreover, by affecting the hedgehog pathway, the down-regulation of FOXR2 blocks thyroid cancer cell invasion and migration caused by hypoxia-induced ROS." (PMID 39866234, 2025).
uterine cancer (1 paper, 2025). Primary or metastatic malignant neoplasm involving the uterine corpus and/or the cervix. "In addition to endometrial carcinoma, FOXR2 is implicated in various malignant tumors, notably uterine cancers like endometrial and cervical carcinomas." (PMID 39866234, 2025).
Wilms tumours (1 paper, 2025). "It is possible, therefore, that FOXR2 rearrangement delineates a particular variant of Wilms tumour in the infant context." (PMID 40442086, 2025). "Searching for further tumours with FOXR2 rearrangement by screening RNA sequencing (RNAseq) data of 264 Wilms tumours for FOXR2 expression, we identified an additional tumour in an older child." (PMID 40442086, 2025).
tumor (29 papers, 2017 to 2025). "The FOXR2 network is intricately linked to tumor development and progression through its roles in promoting cell proliferation, inhibiting apoptosis, enhancing metastasis, and interacting with key oncogenic pathways." (PMID 39866234, 2025). "A total of 42 CNS tumors with FOXR2 overexpression from 41 patients were included in this study, including one patient with CNS NB and a secondary radiation-associated tumor." (PMID 40237561, 2025). "Molecular profiling of serial tumor samples projected the temporal order of mutation acquisition as follows: a somatic L1 insertion at the FOXR2 locus led to aberrant oncogenic FOXR2 expression and chimeric L1/FOXR2 transcripts." (PMID 35403869, 2022). "By understanding the distinct genetic makeup and molecular features of a patient’s tumor, clinicians can design targeted treatment plans that exploit specific vulnerabilities, such as aberrant FOXR2 expression." (PMID 39866234, 2025). "Six patients with PB with FOXR2 overexpression (five classic PB and one pineal anlage tumor) had a mean age of diagnosis of 1.7 years (0.5–5.7 years)." (PMID 40237561, 2025). "While DMGs, HGGs, PBs, MB, and PPTID with FOXR2 overexpression in our cohort exhibited typical histopathologic features of their specific tumor type, FOXR2-activated CNS NB demonstrated substantial variability in histology and immunophenotype." (PMID 40237561, 2025). "Immunohistochemistry analysis indicated a clear link between the level of FOXR2 and key markers of tumor aggressiveness, such as size and proliferation rate." (PMID 39866234, 2025). "This amplification enhances the oncogenic potential of FOXR2, further driving tumor growth and progression." (PMID 39866234, 2025). "All CNS NB-FOXR2 were cerebral cortical tumors, while other CNS tumors with FOXR2 overexpression show regional predilections depending on the specific tumor type." (PMID 40237561, 2025). "RNAi uses siRNAs or shRNAs to silence FOXR2, reducing its expression and potentially inhibiting tumor growth." (PMID 39866234, 2025). "Whereas relapses in patients with PB-miRNA tumors often occur several years after initial diagnosis, tumor relapses in patients with PB-MYC/FOXR2 and PB-RB1 mostly occur rapidly after primary surgery." (PMID 41291966, 2025). "Fluorescein reporting assays confirmed that circABCB10 increased FOXR2 levels by sequestering miR-1252, while animal studies showed that knocking down circABCB10 slowed down tumor growth." (PMID 39866234, 2025). "In OC, members such as FOXA1, FOXM1, FOXP4, FOXQ1, and FOXR2 primarily exhibit oncogenic functions, whereas others like FOXO and FOXP1 are associated with tumor-suppressive effects." (PMID 40746724, 2025). "FOXR2 promotes tumor growth by activating MYC transcription in different human cancer cell lines and tissues, such as breast, lung, and liver." (PMID 39866234, 2025). "As a transcription factor, FOXR2 influences genes that control the cell cycle, apoptosis, and metastasis, thereby promoting tumor growth and progression." (PMID 39866234, 2025). "Gene set enrichment analysis demonstrated shared downstream effects of FOXR2 activation at the epigenome and transcriptome levels across tumor types." (PMID 40237561, 2025). "Factors such as tumor location (supratentorial vs. infratentorial), age at diagnosis, and the presence of molecular markers (e.g., FOXR2, BCOR, CIC, MN1 alterations) are important for differential diagnosis but are not definitive in isolation." (PMID 40647489, 2025). "CNS neuroblastoma, FOXR2-activated is a rare neoplasm, usually occurring in children and frequently located in the cerebral hemispheres." (PMID 37658995, 2024). "Molecularly, this tumor is characterized by FOXR2 rearrangements leading to its activation which are frequently associated with chromosome 1q gain." (PMID 37658995, 2024).